CXCL12 (C-X-C motif chemokine ligand 12)
Diseases named in the same sentence as CXCL12 in open-access papers (continued):
Sharing a sentence is not in itself a finding about the gene and the disease.
lymphoma (39 papers, 2013 to 2026). A malignant (clonal) proliferation of B- lymphocytes or T- lymphocytes which involves the lymph nodes, bone marrow and/or extranodal sites. "The process facilitates lymphoma cell migration toward CXCL12-producing stromal cells and promotes severe bone marrow infiltration." (PMID 40076664, 2025). "We showed that CD19 signaling is required for the CXCL12-induced migration and survival of lymphoma cells." (PMID 40076664, 2025). "Stromal cells, including follicular dendritic cells and macrophages, secrete cytokines and chemokines such as IL-10, TNF-α, and CXCL12, which enhance lymphoma cell survival and proliferation." (PMID 41180747, 2025). "Both the parental peptide and the optimized derivative disrupted CXCL12-mediated signaling, which plays a key role in lymphoma cell migration and survival, especially in CXCR4-expressing malignant B cells." (PMID 40076664, 2025). "While some clones significantly enhanced CXCL12-induced migration, others had minimal effects, highlighting the importance of selecting the appropriate therapeutic clone to target specific lymphoma subtypes." (PMID 40076664, 2025). "Our study highlights the essential role of CD19 in the survival, proliferation, and CXCL12-induced migration of lymphoma cells." (PMID 40076664, 2025). "Case reports have described the expression of CXCL9 on lymphoma cells and its receptor CXCR3 on endothelial cells, as well as in other instances, such as CXCR4 expression on lymphoma cells and its ligand CXCL12 on the endothelium." (PMID 40723240, 2025). "To better understand the role of the endocannabinoid system in lymphoid malignancies, we analyzed how 2-AG regulates the chemotaxis of lymphoma cells and investigated its ability to modify the response to CXCL12 effect on cell migration in MCL and CLL." (PMID 36900374, 2023). "Our results suggest that 2-AG has a previously unrecognized role in the mobilization of lymphoma cells by effecting the CXCL12-induced migration and the CXCR4 signaling pathways, however, with different effects in MCL compared to CLL." (PMID 36900374, 2023). "2-AG on its own is inducing the chemotaxis of most lymphoma cells and it is modulating the CXCL12-mediated chemotaxis that, based on our findings, is dependent on CB1 and CB2 expression levels." (PMID 36900374, 2023). "We specifically aimed at better understanding the role of 2-arachidonoylglycerol in the migration of lymphoma cells, and how it affects the migration towards CXCL12 and specific downstream signaling pathways." (PMID 36900374, 2023). "Our results suggest different mechanisms behind the effects of 2-AG on CXCL12-induced migration in lymphoma cells." (PMID 36900374, 2023). "We demonstrate here that CXCR4-mediated migration of lymphoma cells towards CXCL12 requires the expression of functional ACKR3 at the cell surface." (PMID 36713377, 2022). "Studies showed CXCR4 and its ligand CXCL12 to be expressed by lymphoma cells in PVRL, PCNSL and primary testicular lymphoma (PTL)." (PMID 36233057, 2022). "Pharmacologic or genetic inhibition of BLT1R markedly reduces chemotaxis towards CXCL12 suggesting that LTB4 enhances in a contact-independent manner the migration of lymphoma cells." (PMID 36713377, 2022). "In corresponding bone marrow biopsies, we observed a correlation of CXCL12 expression and lymphoma infiltration rate as well as a reduction of CXCR4 expression in remission of bone marrow involvement after treatment." (PMID 31554271, 2019). "In this study, we observed that CXCL12 is expressed by lymphoma cells and the DLBCL microenvironment." (PMID 31554271, 2019). "The prognostic significance of CXCR4 expression in lymphoma, which has different CXCL12 gradients at the primary sites compared to other types of cancers, has not been well studied." (PMID 25704881, 2015).
lymphoma (continued). "This was selected for CXCR4high lymphoma cells due to the dynamics of CXCL12/CXCR4 equilibrium and led to decreased T cell infiltration and deficient immune responses due to reduced chemoattraction, cooperating with the CXCR4-associated pro-survival signals." (PMID 25704881, 2015). "The exposure of CXCR4- and CXCR7-positive lymphoma cells to CXCL12 greatly potentiates their trans-endothelial migration, and this CXCL12-potentiated transendothelial migration is inhibited by blocking CXCR7." (PMID 24886617, 2014). "However, the enhanced migration capabilities of lymphoma cells toward CXCL12 indicate that CD19’s signaling interaction with CXCR4 is a crucial mechanism in lymphoma cell chemotaxis." (PMID 40076664, 2025). "However, the role of CD19 in promoting CXCL12-induced migration and survival of lymphoma cells remained largely undetermined." (PMID 40076664, 2025). "The inhibition of ACKR3 expression via pharmacological or molecular genetic techniques could impair the migration of lymphoma cells toward CXCL12 and significantly reduce chemotaxis to CXCL12." (PMID 40427609, 2025). "Interfering with this axis by ACKR3 deletion impairs lymphoma cell migration towards CXCL12." (PMID 36713377, 2022). "To investigate if the effects of CXCR4 hyperactivation on B-cell leukemia and lymphoma development and dissemination are B cell intrinsic, we isolated splenocytes of pre-malignant animals and assessed their migratory capacity in response to CXCL12 ex vivo." (PMID 34363012, 2021). "Inhibition of the CXCL12/CXCR4 axis significantly inhibited lymphoma proliferation and survival, suggesting that the CXCR4/CXCL12 axis may participate in EBV-associated lymphomagenesis." (PMID 33052232, 2020). "The data on BM samples with or without involvement of DLBCL of our cohort showed a downregulation of CXCR4 in the BM of patients under remission after therapy as well as the correlation of the CXCL12 expression with lymphoma cell infiltration underpins this assumption." (PMID 31554271, 2019). "Based on our finding that CXCR4 and CXCL12 are expressed simultaneously on lymphoma cells, it might be speculated that an autocrine stimulation loop occurs in aggressive lymphomas." (PMID 31554271, 2019). "Antagonizing scavenging activity of ACKR3 with small molecules or genetic deletion may interfere with the formation of local CXCL12 cues attenuating lymphoma cell dissemination." (PMID 29156704, 2017). "Furthermore, and consistently with our previous results in mice, B cells from P3 lymphoma also showed an increased migration index to CXCL12 with respect to the other samples." (PMID 27297662, 2016). "We speculate that the abnormal CXCR4high/CXCL12low condition at the primary sites lead to the dissemination of CXCR4+ lymphoma cells to distant organs expressing higher CXCL12, which resulted in disease progression of CXCR4+ DLBCL." (PMID 25704881, 2015). "In follicular lymphoma, CXCL12 enhances lymphoma cell movement." (PMID 24859274, 2014). "In addition, the CXCL12/ACKR3/CXCR4 axis was proposed to be involved in lymphoma." (PMID 36713377, 2022). "Our data also demonstrate that forced expression of PCLP1 enhances B-cell lymphoma cell migration toward CXCL12, suggesting that it might direct the dissemination of lymphoma cells to organs expressing this chemokine, including lymph nodes, lungs, liver and bones." (PMID 29245936, 2017). "Moreover, it is unknown whether the use of a CXCL12/CXCR4 antagonist in nodal DLBCL will result in lymphoma cell mobilization and increased spreading." (PMID 25704881, 2015). "Some CXCR4+ GCB-DLBCLs may represent lymphoma cells arising from CXCR4high centroblasts in the CXCL12-rich dark zone and CXCR4− GCB-DLBCLs may be the transformed CXCR4low centrocytes in the light zone, where B cells interact with follicular dendritic and T helper cells." (PMID 25704881, 2015).
lymphoma (continued). "This further demonstrated that ACKR3 enhances CXCL12/CXCR4-mediated intercellular-induced lymphoma migration by promoting LTB4 production, revealing the cell-to-cell-induced migration of lymphoma." (PMID 40427609, 2025). "CXCL12 and its receptor CXCR4 are among the main factors regulating lymphoma cell trafficking from blood to lymphoid tissue." (PMID 36900374, 2023). "On immunohistochemical staining, lymphoma cells were positive for CXCR4 and adenocarcinoma cells were positive for CXCL12/SDF-1." (PMID 34187383, 2021). "We also demonstrated that CXCL12 expression correlated to the BM infiltration rate and that CXCR4 was lower expressed in BM samples from patients exhibiting a remission of lymphoma infiltration after therapy." (PMID 31554271, 2019). "Lymphoma cells express the C-X-C chemokine receptor type 4 (CXCR4), which mediates cell migration to organs expressing its ligand C-X-C motif chemokine 12 (CXCL12)." (PMID 29245936, 2017). "Decreased CXCR4 resulted in disrupt lymphoma and host bone marrow-derived stromal cells CXCR4/CXCL12 axis, what resulted in stroma-induced protection from immunotherapy infringement." (PMID 24859274, 2014). "Knowing the essential role of CD19 in the survival and CXCL12-induced migration of both BCWM.1 and DHL6 lymphoma cells, we tested whether treatment with anti-CD19 monoclonal antibodies (mAbs) had any effect on these cells." (PMID 40076664, 2025). "Additionally, the lymphoma cell line BL2, which is known to strongly express CXCR4 and to migrate toward CXCL12 in transwell migration assays, was included." (PMID 31554271, 2019). "A few case reports described the presence of CXCL9 and CXCR3 17, as well as CXCL12 and CXCR4 18, on lymphoma cells and these CXC chemokines may serve as positive regulators for the lymphoma cells to aggregate in specific intravascular space." (PMID 24931821, 2014). "To investigate the role of 2-AG in lymphoma, we analyzed the chemotactic response of primary B-cell lymphoma cells enriched from peripheral blood of twenty-two chronic lymphocytic leukemia (CLL) and five mantle cell lymphoma (MCL) patients towards 2-AG alone and/or to the chemokine CXCL12." (PMID 36900374, 2023). "Comparison of CXCR4 and CXCL12 mRNA expression levels in BM specimens with and without lymphoma infiltration at time of diagnosis showed a 1.6-fold higher CXCR4 expression in BM specimens exhibiting lymphoma infiltration (p = 0.008)." (PMID 31554271, 2019).
HIV-1 infection (36 papers, 2005 to 2026). The type species of lentivirus and the etiologic agent of acquired immunodeficiency syndrome (AIDS). "On the other hand, the opposite effects of CXCL12 were also reported, linking this chemokine to the neuronal death under neuropathological conditions associated with HIV-1 infection." (PMID 33983546, 2021). "The binding of the chemokine CXCL12 (SDF1) to its receptor CXCR4 has been implicated in HIV-1 infection and cancer metastases." (PMID 28848546, 2017). "The chemokine receptor CXCR4 and its ligand CXCL12 regulate leukocyte trafficking, homeostasis and functions and are potential therapeutic targets in many diseases such as HIV-1 infection and cancers." (PMID 36770826, 2023). "Only recently, dendritic simplification and cognitive flexibility in a transgenic rat model of HIV-1 infection was rescued by CXCL12, an endogenous chemokine and antagonistic ligand for the CXCR4 receptor, presumably outcompeting gp120 interaction with CXCR4." (PMID 33705493, 2021). "The dimeric EPI-X4 derivative WSC02x2 showed a Ki of 69 nM, which is ~ tenfold lower than that of the endogenous peptide and reflects also its enhanced potency in inhibiting CXCR4-tropic HIV-1 infection and CXCL12-dependent cell migration." (PMID 32994431, 2020). "We conclude that CXCL14 was unable to synergize with CXCL12 in the inhibition of HIV-1 infection, but, instead, substantially enhanced the infection of CD4+ target cells with both X4 and R5 HIV-1 particles." (PMID 28360196, 2017). "Inclusion of increasing concentrations of CXCL12 seemed to diminish the enhancement of X4 HIV-1 infection by CXCL14, which is in agreement with the critical role played by CXCR4 in this process." (PMID 28360196, 2017). "AMD3100 (Plerixafor) is a selective CXCR4 chemokine receptor antagonist that blocks the interaction between CXCR4 and its natural ligand CXCL12, a critical axis involved in various pathological conditions, including HIV-1 infection, tumor progression, and metastasis." (PMID 40698080, 2025). "Thus, with the exception of MSX122 and CTCE-9908, all analyzed CXCR4 ligands bind CXCR4, prevent 12G5-antibody binding, CXCL12-induced cellular migration and X4-tropic HIV-1 infection." (PMID 32994431, 2020). "Previous studies already showed that post-translational modifications may strongly affect the ability of CXCL12 to inhibit HIV-1 infection." (PMID 30233568, 2018). "As expected, CXCL12 was completely inactive in the prevention of R5 HIV-1 infection." (PMID 28360196, 2017). "CCL3, CCL4, CCL5 and CXCL12 are important natural inhibitors of HIV-1 infection, and it possible that the activation of chemokine receptors may stimulate chemokine expression." (PMID 21264298, 2011). "Furthermore, these ligands induced oligomerization of CXCR4R334X, a naturally occurring mutant associated with WHIM syndrome that supports HIV-1 infection, but fails to oligomerize in response to CXCL12." (PMID 42118136, 2026). "CXCL12 and CXCR4 knockout mice are embryonic lethal and signaling through the CXCL12/CXCR4 axis has been implicated in organogenesis, autoimmunity, WHIM syndrome (Warts, Hypogammaglobulinemia, Infections, and Myelokathexis), and human immunodeficiency virus -1 (HIV-1) infection." (PMID 21949786, 2011). "As expected, CXCL12 and AMD3100 specifically inhibited CXCR4-tropic HIV-1 infection, with IC50 values of 47.9 ± 8 nM and 5.3 ± 0.4 nM, respectively, while Maraviroc blocked CCR5-tropic HIV-1 infection." (PMID 40394646, 2025). "To examine whether GPR15LG binding to CXCR4 interferes with HIV-1 infection, we incubated TZM-bl reporter cells with GPR15LG, CXCL12, AMD3100, and the CCR5 antagonist Maraviroc and subsequently infected them with CXCR4- or CCR5-tropic HIV-1." (PMID 40394646, 2025). "CXCL12 within mucosa and lymph nodes was proposed to counter-select transmission of CXCR4-using viruses, thereby contributing to preponderance of R5 viruses in the first stages of HIV-1 infection." (PMID 33872329, 2021).
HIV-1 infection (continued). "We also showed that CXCL12/SDF-1 blocked T-tropic HIV-1 infection at an early step without affecting the rest of the HIV-1 life cycle by setting up two complementary experiments." (PMID 26097474, 2015). "A greater understanding of CXCL12/CXCR4 signaling pathways may lead to more selective therapeutics for diseases such as cancer and HIV-1 infection." (PMID 21949786, 2011). "A recent study has shown that NK cells from non-pregnant uterine mucosa can inhibit X4 HIV-1 infection by secreting high levels of CXCL-12." (PMID 21767373, 2011). "Production of IL-12, IL-6, CCL-2, CXCL-10 and CXCL-12, that were also detected at day 14, was not significantly affected by either R5 or X4 HIV-1 infection (data not show)." (PMID 21767373, 2011). "Moreover, CXCR4 in the proteoliposomes binds CXCL12, the natural ligand, and AMD3100, a small-molecule inhibitor of HIV-1 infection." (PMID 20967243, 2010). "Of note, CXCL14 did not synergize with CXCL12 in its HIV-1 suppressor activity (i.e., CXCL14 did not increase the potency of CXCL12 to inhibit HIV-1 infection)." (PMID 28360196, 2017).
autoimmune disease (35 papers, 2006 to 2026). A disorder resulting from loss of function or tissue destruction of an organ or multiple organs, arising from humoral or cellular immune responses of the individual to their own tissue constituents. "ACKR3 is an atypical chemokine receptor associated with some autoimmune diseases and inflammatory responses, and the CXCL12/CXCR4/ACKR3 axis is a potential therapeutic target for several inflammatory diseases." (PMID 36118358, 2022). "CXCL12 is a homeostatic chemokine that is highly expressed and secreted within the tumor-associated hypoxic and proangiogenic environment and during the autoimmune disease-related activities." (PMID 34413914, 2021). "CXCR4 and CXCL12 have been implicated in the pathogenesis of autoimmune diseases." (PMID 27005825, 2016). "In addition, distinct B cell populations, designated regulatory B (Breg) cells, produce the anti-inflammatory cytokine CXCL12 (C-X-C Motif Chemokine Ligand 12), which maintains the balance of the immune response and restrains immune responses associated with autoimmune diseases." (PMID 37372966, 2023). "In summary, the CXCR4/CXCL12 axis represents a shared immune dysregulation pathway connecting multiple autoimmune diseases." (PMID 41481752, 2026). "CXCL12, an anti-inflammatory chemokine in autoimmune diseases, is involved in a variety of inflammatory responses, and it blocks and attenuates inflammatory responses." (PMID 39409044, 2024). "The CXCL12/ACKR3 axis has been previously recognized to play a crucial role in various autoimmune diseases." (PMID 39215271, 2024). "Decreased expression and activation levels of CXCL12 were found in cyclosporin-immunosuppressed B cells as a mechanism for the treatment of autoimmune diseases by this class of drugs." (PMID 36793719, 2023). "One example of this relationship is between CXCL12 as a driver of autoimmune diseases and its role in activating BTK as part of the chemotaxis process." (PMID 34803999, 2021). "Recently, the CXCL12/CXCR4/CXCR7 axis was associated with cancer metastasis and autoimmune diseases." (PMID 34764871, 2021). "The available evidence thus indicates that CXCL12 restricts the intraparenchymal migration of mononuclear cells during autoimmune disease at the CNS." (PMID 31507535, 2019). "Here, we review the involvement of the CXCL12/CXCR4/ACKR3 axis in some of the most prevalent autoimmune diseases: psoriasis, multiple sclerosis, rheumatoid arthritis, lupus, type I diabetes (T1D), and inflammatory bowel disease." (PMID 31507535, 2019). "As a homeostatic chemokine, CXCL12 plays a regulatory role in autoimmune diseases." (PMID 40001479, 2025). "Involvement of the CXCR4/CXCL12 axis is also reported in other autoimmune diseases." (PMID 38519141, 2024). "Continuing the hypothesis that CXCL12 is a driver of autoimmune diseases, a multi targeted approach for inhibiting BTK and other kinases could have beneficial effects." (PMID 34803999, 2021). "Although the precise mechanism underlying the discrepancy between the two studies has yet to be determined, our finding provides a basis for further exploring the use of AMD3100 to prevent and/or treat TID and possibly other autoimmune diseases in patients with elevated CXCL12 or CXCR4 expression." (PMID 18793419, 2008). "That HMGB1 with the receptors CXCL12 and CXCR4 is also involved in autoimmune diseases has already been reported." (PMID 34943212, 2021). "The present review discusses the role of the CXCL12/CXCR4/ACKR3 axis in inflammation, focusing on its involvement in several autoimmune diseases." (PMID 31507535, 2019). "Moreover, as stromal-cell-derived factor-1 (SDF-1), CXCL12 plays a crucial role in regulating immune responses, particularly in autoimmune diseases such as inflammatory bowel disease." (PMID 40001479, 2025).
autoimmune disease (continued). "The chemokine CXCL12 and its two cognate receptors—CXCR4 and ACKR3—are key players in various homeostatic and pathophysiological processes, including embryonic development, autoimmune diseases, tissue repair, and cancer." (PMID 39662834, 2024). "In autoimmune diseases such as SLE, increased expression of chemokine receptors (CXCR2, CXCR3, CCR3 and CCR1) and elevated levels of chemokines such as MCP-1/CCL2, MIP-1/CCL-4, SDF-1/CXCL-12, RANTES/CCL5 and IP-10/CXCL-10 are observed." (PMID 36059466, 2022). "The chemokine CXCL12 (SDF-1) and its cognate receptor CXCR4 are involved in a large number of physiological processes including HIV-1 infectivity, inflammation, tumorigenesis, stem cell migration, and autoimmune diseases." (PMID 27456816, 2016).